ATRX (ATRX chromatin remodeler)
Diseases named in the same sentence as ATRX in open-access papers (continued):
Sharing a sentence is not in itself a finding about the gene and the disease.
neuroblastoma (continued). "However, the data on the incidence of ATRX mutation and clinical significance in MYCN non-amplified neuroblastoma is limited." (PMID 40286729, 2025). "A significant challenge in the field is the lack of available models of ATRX mutant neuroblastoma." (PMID 39892705, 2025). "A subset of genes that are normally induced in MYCN-amplified neuroblastomas also may have failed to be activated in the ATRX-mutant neuroblastomas owing to the DNA and/or histone modifications." (PMID 32060267, 2020). "In this study, 37 tumors from MYCN non-amplified neuroblastoma patients were sequenced and the authors found two older children (NB1 and NB2) with advanced MYCN non-amplified neuroblastoma carried each one of the two following novel nonsense ATRX variants (p.Gln1670* or p.Glu1984*)." (PMID 40286729, 2025). "A neuroblastoma-specific panel using NGS could be developed to identify more comprehensive genomic information to molecularly treat and predict prognosis with sophistication based on genomic characteristics such as MYCN, TERT, ATRX, ALK, ARID1, and telomere length." (PMID 28521285, 2017). "The analysis of two additional available datasets of neuroblastoma patients -TARGET-NB and GSE62564.Fischer – consistently showed a negative correlation between ATRX expression and macrophage scores." (PMID 39892705, 2025). "These analyses are of utmost relevance in neuroblastomas without MYCN-amplification, TERT rearrangement, and ATRX alterations, as these neuroblastomas are most likely low-risk, but the detection of telomerase overexpression or ALT would still render them high-risk." (PMID 34442335, 2021).
Alpha-thalassemia (71 papers, 2010 to 2025). Alpha-thalassemia is an inherited hemoglobinopathy characterized by impaired synthesis of alpha-globin chains leading to a variable clinical picture depending on the number of affected alleles. "ATRX stands for X-linked alpha-thalassemia/mental retardation syndrome, due to its initial identification in patients with severe psychomotor retardation, characteristic facial features, genital abnormalities, and alpha-thalassemia." (PMID 41422096, 2025). "Further mechanisms such as epigenetic changes within tumor cells and mutations in DAXX (death-domain-associated protein) or ATRX (alpha thalassemia/mental retardation syndrome X-linked) have also been proposed." (PMID 40384778, 2025). "MRI: magnetic resonance imaging; PCR: polymerase chain reaction; ATRX: alpha-thalassemia/mental retardation syndrome X-linked gene." (PMID 40896065, 2025). "Further genetic testing, including alpha-thalassemia/mental retardation, X-linked (ATRX), telomerase reverse transcriptase promoter (TERTp), and O-6-methylguanine-DNA methyltransferase (MGMT), would be beneficial but was difficult to conduct in this study." (PMID 39917141, 2025). "Loss of the alpha-thalassemia/mental retardation, X-linked (ATRX) chromatin remodeller is a common event in ALT-positive cancers, but is generally insufficient to drive ALT induction in isolation." (PMID 39657822, 2024). "The stemness index was significantly lower in alpha-thalassemia/mental retardation, X-linked (ATRX) mutant samples than in wild-type samples but significantly higher in the telomerase reverse transcriptase (TERT) mutant group." (PMID 38229597, 2024). "Two cases had a somatic MEN1 missense mutation and one case an ATRX (Alpha Thalassemia/intellectual disability syndrome X-linked) missense mutation." (PMID 37771441, 2023). "Hypomorphic mutations in the X-linked ATRX gene cause a rare form of intellectual disability combined with alpha-thalassemia called ATR-X syndrome in hemizygous males." (PMID 37171606, 2023). "ATRX (alpha-thalassemia/intellectual disability, X-linked) was initially identified as a trans-acting factor which when mutated downregulates alpha-globin expression." (PMID 37171606, 2023). "Alpha-thalassemia/mental retardation, X-linked (ATRX), which controls the establishment of pericentromeric heterochromatin regions, is essential for Sertoli cell proliferation and survival." (PMID 35769260, 2022). "Gene ATRX (Alpha thalassemia/mental retardation syndrome X-linked chromatin remodeler) was first discovered in the X-linked mental retardation syndrome (ATRX syndrome) patients." (PMID 36531058, 2022). "The ATMDS is in contrast due to ATRX gene somatic mutations in blood cells presenting more severe alpha-thalassemia." (PMID 35444965, 2022). "For instance, circRNA mitochondrial translation optimization 1 homologue promoted OSCC cell proliferation, migration, and invasion in vitro via miR-320a/alpha thalassemia/mental retardation, X-linked (ATRX) axis." (PMID 35635053, 2022). "ATRX (Alpha-Thalassemia/Mental Retardation Syndrome, X-Linked) encodes a protein that contains an ATPase/helicase domain, and thus it belongs to the SWI/SNF family of chromatin remodelling proteins." (PMID 35975235, 2022).
Alpha-thalassemia (continued). "In many ALT cancers, the α‐thalassemia/mental retardation syndrome X‐linked (ATRX) gene is mutated leading to the conclusion that the ATRX complex represses ALT." (PMID 35920001, 2022). "The alpha thalassemia/intellectual disability, X-linked (ATRX) protein is an SNF2-type ATP-dependent chromatin remodeller/helicase that maintains chromatin over repetitive DNA regions, such as pericentric heterochromatin and telomeres." (PMID 34780483, 2021). "Our study investigated the role of circMTO1 in OSCC and found that circMTO1 knockdown inhibits cancer progression by protecting Alpha Thalassemia/Mental Retardation, X-linked (ATRX) from miR-320a regulation in OSCC cells." (PMID 34738503, 2021). "The most frequently mutated gene in our LEB-GBM cohort is ATRX (alpha-thalassemia/mental retardation, X-linked) with 70.0% (95% CI: 58.4–81.6; n = 42/60) samples affected by 16 different types of missense variants." (PMID 33237934, 2020). "Alpha-thalassemia/mental retardation, X-linked, or ATRX, is an autism susceptibility gene that encodes a chromatin remodeler." (PMID 32580781, 2020). "Characteristics of the sporadic form of PNETs are mainly gene mutations in DAXX (death-domain-associated protein) or ATRX (alpha thalassemia/mental retardation syndrome X-linked)." (PMID 33384663, 2020). "The major genetic alteration associated with ALT is loss of alpha thalassemia/mental retardation syndrome X-linked chromatin remodeler (ATRX), and reintroduction of ATRX results in repression of ALT." (PMID 31895940, 2020). "At the global level, there were two highly connected genes, AGPS (Alkylglycerone Phosphate Synthase) and ATRX (Alpha Thalassemia/Mental Retardation Syndrome, X-Linked), regulated dozens of genes directly (41 and 32 respectively)." (PMID 31569720, 2019). "Previous work in our lab had identified ATRX chromatin remodeler (ATRX), previously termed, Alpha Thalassemia/Mental Retardation Syndrome X Linked as a gene mutated in a subset of MPNSTs." (PMID 29796169, 2018). "Among the rapidly expanding number of proteins responsible for chromatin maintenance and remodeling related to transcription is alpha thalassemia/mental retardation X-linked (ATRX; NG_008838.2)." (PMID 28293299, 2017). "The ATRX L2237P mutation (chromosome X: 76,778,869 A>G) observed on the single male-derived X chromosome, lies within the gene encoding for the alpha thalassemia/mental retardation syndrome X-linked protein implicated in chromatin remodeling." (PMID 28423598, 2017). "We also evaluated the protein loss of O-6-methylguanine-DNA methyltransferase (MGMT) and alpha-thalassemia/mental retardation, X-linked (ATRX) during disease recurrence." (PMID 29026176, 2017). "Note that these TSC2 gene mutations have not been detected as frequently as multiple endocrine neoplasia type 1 (MEN1) and death domain-associated protein/alpha thalassemia/mental retardation syndrome X-linked (DAXX/ATRX) gene mutations." (PMID 25889454, 2015). "For example, the mouse ATRX (alpha thalassemia/mental retardation syndrome X-linked) expression pattern is negatively correlated with human (rho = −0.36, q = 0.09)." (PMID 23440889, 2013). "Such a link has been elusive despite the fact that clinical mutations of the ATRX gene lead to a downregulation of alpha-globin resulting in alpha-thalassaemia." (PMID 21676266, 2011). "ATRX is a severe X-linked disorder characterized by mental retardation, facial dysmorphism, urogenital abnormalities and alpha-thalassemia." (PMID 20602808, 2010). "The ATRX (alpha-thalassemia/mental retardation syndrome X-linked) and DAXX (death-domain associated protein) genes are involved in the ATRX/DAXX pathway, which is frequently mutated in pNETs, particularly those that are well differentiated and advanced or metastatic." (PMID 40429384, 2025).
Alpha-thalassemia (continued). "In addition, ATRX is associated with a dominantly inherited form of alpha‐thalassemia/impaired intellectual development syndrome in human patients (OMIM 301040)." (PMID 40525707, 2025). "Therefore, ATRX gene mutations are associated to X-linked syndromes with cognitive disabilities as well as alpha-thalassemia (ATRX) syndrome." (PMID 36624117, 2023). "Previously reported cases carrying ATRX variants with alpha-thalassemia." (PMID 35444965, 2022). "Animal studies demonstrate that disruption of AT-hook 2 domain causes chromatin disorganization, a loss of chromatin remodeling protein ATRX (alpha thalassemia/mental retardation syndrome X-linked) from the heterochromatin, and mislocalization of ATRX within the nervous system." (PMID 29137252, 2017). "Loss of ATRX (alpha thalassemia/mental retardation syndrome X-linked) protein and mutations in the ATRX gene are associated with genome instability, defects in the G2/M checkpoint, and altered double strand break (DSB) repair in alternative lengthening of telomeres pathway." (PMID 25268703, 2014). "Another issue for future investigations is suggested by the observation that somatic mutations of ATRX are associated with alpha thalassaemia myelodysplastic syndrome, an acquired form of alpha-thalassaemia that most commonly arises in the context of myelodysplasia." (PMID 20602808, 2010). "The N- and C-terminus mutations of ATRX protein may cause a milder phenotype of alpha-thalassemia." (PMID 35444965, 2022). "Interestingly, U2OS cells are deficient in ATRX (alpha thalassemia/mental retardation X-linked)." (PMID 32332163, 2020). "Hereditary mutations of ATRX have been described in association with XLMR syndrome (X-linked mental retardation syndrome) and alpha-thalassemia." (PMID 38674026, 2024). "Genetic variants of ATRX are associated with a variety of diseases including ATR-X, MRXHF1, and alpha-thalassemia associated with myelodysplastic syndromes (ATMDS) (OMIM#300448)." (PMID 35444965, 2022). "Germline ATRX mutations cause ATR-X Syndrome, a rare X-linked disorder characterized by alpha thalassemia and intellectual disability." (PMID 34780483, 2021). "BAZ2B (Bromo-domain Adjacent to Zinc finger domain 2B), which binds to acetylated histone H3 lysine 14 (H3K14Ac) and the chromatin remodeler ATRX (Alpha Thalassemia/mental Retardation syndrome X) also correlate with elevated R/G ratios." (PMID 34174884, 2021). "Mutations in the ATRX gene cause ATR-X syndrome, an X-linked recessive developmental disorder resulting in severe mental retardation and mild alpha-thalassemia with facial, skeletal and genital abnormalities." (PMID 21676266, 2011). "Alpha-thalassemia X-linked mental retardation syndrome (ATRX; OMIM #301040) is caused by mutation of the ATRX gene." (PMID 20163734, 2010). "With the recent development of exome sequencing (ES), ATRX gene variants of severe to profound intellectual disability without alpha-thalassemia have been implicated in intellectual disability-hypotonic facies syndrome, X-linked, 1(MRXHF1, OMIM #309580)." (PMID 35444965, 2022). "Although alpha-thalassaemia is commonly present, some patients with the ATRX gene variants do not express this symptom, which showed a wide spectrum of other pathological features." (PMID 35444965, 2022). "In one case without TERT-promoter mutation an alpha thalassemia/mental retardation syndrome, X-linked (ATRX)-frameshift insertion was detected." (PMID 33876327, 2021). "Immunohistochemistry demonstrated lack of ATRX (alpha thalassemia/mental retardation syndrome X-linked) protein in tumor cells, indicating an ATRX gene mutation." (PMID 34888235, 2021).
Alpha-thalassemia (continued). "Mutations in ATRX cause X-linked alpha thalassaemia mental retardation (ATR-X syndrome) in males, which is associated with profound developmental delay, facial dysmorphism, genital abnormalities and alpha thalassemia." (PMID 24690944, 2014). "It is well-known that hematologic findings vary widely among ATRX patients and in some cases the manifestation of alpha-thalassemia may be subtle." (PMID 20602808, 2010). "Furthermore, it should be noted that individuals with germline inactivating mutations or deletions in ATRX, do not have a cancer predisposition syndrome, even in the male population who manifest the alpha thalassemia/mental retardation X-linked syndrome." (PMID 29796169, 2018). "Alpha thalassemia/mental retardation syndrome X-linked chromatin remodeler (ATRX), a DAXX (death domain-associated protein) interacting protein, is often lost in cells using the alternative lengthening of telomeres (ALT) pathway, but it is not known how ATRX loss leads to ALT." (PMID 31895940, 2020).
α-thalassemia (58 papers, 2008 to 2026). "Germline mutations in the chromatin remodelling protein ATRX cause a severe developmental disorder associated with α-thalassemia." (PMID 41688464, 2026). "Generally, ALT is activated by loss-of-function (LOF) genetic alterations in the chromatin remodelers α thalassemia-mental retardation, X linked (ATRX) and death domain-associated protein 6 (DAXX)." (PMID 39224814, 2024). "These mutations also include chromatin remodelers such as SETD2; α-thalassemia/mental retardation, X-linked (ATRX); and DAXX." (PMID 36647827, 2023). "Studies recently highlighted the α-thalassemia/mental retardation syndrome X-linked (ATRX) gene as a central player in genome stability and function maintenance." (PMID 37373974, 2023). "The ATRX gene, also known as ATP-dependent helicase ATRX, is the pathogenic gene of thalassemia with mental retardation syndrome." (PMID 37570630, 2023). "Although deficiency of ATRX causes α-thalassaemia, the red cell phenotype is quite different to that seen in the common forms of this anaemia." (PMID 35710802, 2022). "Nuclear expression of ATRX (nuclear immunopositivity for α-thalassemia/mental-retardation-syndrome-X-linked) was retained, and there was expression of IDH1 (isocitrate dehydrogenase 1) R132H mutant protein." (PMID 35018523, 2022). "These individuals had the same ATRX mutation but only one of them (case 1) had a detectable α-thalassaemia phenotype with 3% of red cells exhibiting HbH (β4) inclusions." (PMID 35710802, 2022). "Inactivating mutations in the ATRX gene lead to an X-linked condition called ATRX syndrome manifested as intellectual disability, α-thalassemia, genital abnormalities, and facial malformation." (PMID 34680266, 2021). "In the nucleus, DAXX interacts with transcription factors, epigenetic modifiers, and chromatin-remodeling proteins such as the transcription regulator ATRX—the α-thalassemia/mental retardation syndrome X-linked ATP-dependent helicase II." (PMID 33525665, 2021). "Mutations in ATRX (α-thalassemia/mental retardation syndrome X-linked) and DAXX (death domain associated protein) have been frequently observed in pNETs." (PMID 34680266, 2021). "The objective of this study was to analyze the expression and clinical role of mitosis regulators α-thalassemia/mental retardation syndrome X-linked (ATRX) and death-domain-associated protein (DAXX) in metastatic high-grade serous carcinoma (HGSC)." (PMID 32533344, 2020). "Nuclear expression of ATRX (nuclear immunopositivity for α-thalassemia/mental-retardation-syndrome-X-linked) was retained and there was no expression of IDH1 (isocitrate dehydrogenase 1) R132H mutant protein." (PMID 32451719, 2020). "Some mutations have been shown to disrupt conserved AT-hook regions and cause differential localization of α-Thalassemia/Mental Retardation Syndrome X-Linked (ATRX)." (PMID 33363010, 2020). "It has a crucial role in the development of organs from all 3 germ cell layers, as evidenced by the fact that mutations in it are the sole cause for ATRX (α-thalassemia, mental retardation, X-linked) syndrome." (PMID 32533344, 2020). "ATRX acts as a negative regulator of macroH2A1 deposition at telomeres and α-globin cluster and dysfunctional regulation is linked to the α-thalassemia phenotype in ATRX syndrome patients." (PMID 29034211, 2017). "Mutations in the ATRX gene were found to cause impaired contextual fear memory in mice and α-Thalassaemia/mental Retardation X-linked syndrome in humans." (PMID 26635563, 2015).